CD99 (CD99 molecule (Xg blood group))
Diseases named in the same sentence as CD99 in open-access papers (continued):
Sharing a sentence is not in itself a finding about the gene and the disease.
osteosarcoma (20 papers, 2010 to 2025). A usually aggressive malignant bone-forming mesenchymal neoplasm, predominantly affecting adolescents and young adults. "Conversely, loss of CD99 expression has been described in osteosarcoma, suggesting a tumor suppressor role of CD99 in this particular cellular context." (PMID 28903388, 2017). "In order to compare our experiments with the previously published data, we additionally transfected U2-OS (osteosarcoma) cells with CD99 WT or the cancer associated variants D92H and D92Y." (PMID 28903388, 2017). "However, in other cancers (such as osteosarcoma and gastric cancer), decreased CD99 expression is associated with tumour progression." (PMID 34374417, 2021). "In osteosarcoma, CD99 transfection inhibits tumor metastasis by suppressing c-Src and ROCK2 activities." (PMID 40427525, 2025). "CD99 is low in tumors like Hodgkin’s lymphomas, osteosarcomas, pancreatic tumors, gallbladder and gastric carcinomas, and certain pulmonary neuroendocrine tumors, while present in normal tissues." (PMID 40427525, 2025). "Outgoing and incoming signalling pattern analyses indicated that signalings such as Collagen, MK, MIF, PTN and CD99 dominated the intercellular communication modes among cells within osteosarcomas." (PMID 39834330, 2025). "CD99 expression in osteosarcoma and stomach cancer reduces proliferation, migration, and metastasis while increasing differentiation." (PMID 40427525, 2025). "A study in osteosarcoma demonstrated that CD99 exogenous expression inhibits cell migration through inhibition of Src and Rock2." (PMID 33147457, 2020). "In osteosarcoma, exogenous CD99 was shown to inhibit osteosarcoma cell migration through inhibition of Src and Rock2." (PMID 33147457, 2020). "Anti-CD99 antibodies induced by the TRXtr-mCD99 were able to detect native CD99 in osteosarcoma tumor tissue." (PMID 31001265, 2019). "In the CT26 model only low levels of CD99 are expressed by the tumor cells as compared to the osteosarcoma model." (PMID 31001265, 2019). "In order to determine the CD99 expression in the murine osteosarcoma (Os-P0107) and colon carcinoma (CT26) cell lines qPCR primers were designed to determine the expression of endogenous CD99 (mCD99; RefSeq NP_079860.2." (PMID 31001265, 2019). "Osteosarcoma tumor tissue of the first vaccination study (study I) was stained for the vascular marker CD31 to determine the effect of vaccination against CD99 on the tumor vasculature." (PMID 31001265, 2019). "The osteosarcoma model highly expresses CD99 and therefore inhibition of tumor growth in this model is due to targeting of both the tumor vasculature and the tumor cells, which leads to a more pronounced anti-tumor effect." (PMID 31001265, 2019). "Up to now, data available in osteosarcoma, only pointed out the importance of the presence of the Ser168 residue of CD99: Ser168 is required for the CD99wt-mediated inhibition of migration and metastatization of osteosarcoma and prostate cancer cells." (PMID 29534016, 2018). "CD99 forms stable complexes with caveolin-1, a molecule with oncosuppressor functions in osteosarcoma, and c-Src, which is therefore maintained in its inactive conformation." (PMID 29534016, 2018). "In osteosarcoma, transfection of CD99 inhibited tumor metastasis through the suppression of c-Src and Rho-associated, coiled-coil-containing protein kinase 2 (ROCK2) activities." (PMID 29534016, 2018). "As EWS cells are not the best model to study endocytosis, having large nuclei, small cytoplasm and growing in suspension, we alternatively used U-2 OS osteosarcoma cells transfected with CD99." (PMID 27835596, 2016). "Treatment of EWS or osteosarcoma U2/CD99wt57 cells with 0662mAb triggered CD99 internalization, as shown by a significant decrease of CD99 cell surface levels measured by both flow cytometry and ELISA assay." (PMID 27835596, 2016).
osteosarcoma (continued). "This is in agreement with our previous demonstration showing that whenever CD99 expression was regained by osteosarcoma cells, they reactivate the terminal osteoblastic differentiation program." (PMID 26000312, 2015). "It has been shown that CD99-forced expression considerably affects osteosarcoma cell behavior reversing their cell malignancy by regulating critical biological processes required for metastases." (PMID 26000312, 2015). "The current paper explores temporal transcriptional modifications comparing an osteosarcoma cell line, Saos-2, and clones stably transfected with CD99, a molecule which was found to drive OS cells to terminally differentiate." (PMID 26123714, 2015). "New data also provide evidence that when CD99 is restored in osteosarcoma cells, the molecule favors terminally differentiated phenotype." (PMID 26000312, 2015). "In line with the recent demonstration that CD99-restored expression in osteosarcoma cell correlated with ERK 1/2, RUNX2, and AP-1 activation, we here show that PI3K and ERK1 K inhibitors rescue COLLI, RUNX2 and JUND OB protein levels." (PMID 26000312, 2015). "A splice variant of CD99 increases motility and MMP-9 expression of human breast cancer cells, in osteosarcoma and prostate cancer." (PMID 20175889, 2010). "CD99 has been shown to inhibit Src by an unknown mechanism in osteosarcoma and acute myeloid leukemia." (PMID 33147457, 2020). "Targeting of murine CD99 by a conjugate vaccine, which induced antibodies against CD99 in mice, resulted in inhibition of tumor growth in both a tumor model with high CD99 (Os-P0109 osteosarcoma) and low CD99 (CT26 colon carcinoma) expression." (PMID 31001265, 2019). "Indeed, the Western blot confirmed that the osteosarcoma cells express high levels of murine CD99 (24 kDa, green band) and that CD99 expression in the CT26 cell line is much lower." (PMID 31001265, 2019). "In addition, the ratio of the CD99 and β-actin bands was quantified with ImageJ software and the osteosarcoma cell line showed a higher CD99/β-actin ratio than the CT26 cell line (Os-P0107 ratio: 1.77; CT26 ratio: 0.46)." (PMID 31001265, 2019). "Therefore, we stained tissue of Os-P0107 osteosarcoma tumors derived from TRXtr-vaccinated mice with serum of TRXtr-mCD99 (CD99) vaccinated mice or of control (TRXtr) vaccinated mice." (PMID 31001265, 2019). "Indeed, when antibodies against CD99 were present in the sera of the mice, tumor growth of osteosarcoma (Os-P0107) was significantly inhibited compared to control vaccinated mice (**P < 0.01)." (PMID 31001265, 2019). "Notably, the forced expression of CD99 in osteosarcoma and/or in stomach cancer cell lines has been observed to reduce proliferation, migration, and metastasis capabilities, while increasing cell differentiation." (PMID 29534016, 2018). "Additionally, CD99 was shown to inhibit Src by an unknown mechanism in osteosarcoma and acute myeloid leukemia." (PMID 33147457, 2020). "CD99 isoforms also dictate different functions in malignancy, exerting opposite effects on crucial biological processes, such as migration/invasion, growth in anchorage-independent conditions, and differentiation and metastasis in osteosarcoma, prostate cancer, and breast carcinoma." (PMID 29534016, 2018). "In Hodgkin’s lymphomas, osteosarcomas, pancreatic tumors, gallbladder carcinomas, gastric carcinomas and in pulmonary neuroendocrine tumors of diverse histological types, CD99 is expressed at low levels, whereas the molecule is present in the respective normal tissues." (PMID 29534016, 2018). "Genome-wide studies have identified genes and pathways involved in osteosarcoma progression and metastasis, including WNT/β-catenin, Notch, and CD99, emphasizing the importance of precision medicine in diagnosis and treatment." (PMID 39896817, 2024). "Conversely, CD99 is downregulated or completely lacking in pancreatic endocrine neoplasm, gastric adenocarcinoma, and osteosarcoma." (PMID 26000312, 2015).
osteosarcoma (continued). "After vaccination against CD99 we found more vessels without pericytes in the osteosarcoma tumors." (PMID 31001265, 2019). "Thus, GD2, CD9, CD105, and CD71 were positive in two osteosarcomas (OS), while CD90 was expressed in only one case, always in the absence of nuMyoD1, numyogenin, CD57, and CD99 expression." (PMID 34638431, 2021).
primitive neuroectodermal tumor (17 papers, 2013 to 2025). A malignant neoplasm that originates in the neuroectoderm. "The tumor cells were negative for epithelial markers (cytokeratin AE1/AE3 and EMA), lymphoid markers (CD45), and markers of primitive neuroectodermal tumors (CD99)." (PMID 41322068, 2025). "Histopathological analysis revealed a renal small round blue cell tumor (consistent with a primitive neuroectodermal tumor), with positive immunohistochemistry for CD99 and Ki67 (about 10%) and molecular pathology for EWSR1 gene fusions." (PMID 35821028, 2022). "The diagnosis of Ewing sarcoma/primitive neuroectodermal tumors was made due to CD99 positive expression." (PMID 29390485, 2017). "Other immunohistochemical markers include CD99 which is mostly present in neuroectodermal tumors and could be a potential marker for sex-cord stromal tumors due to its presence in granulosa and Sertoli cells." (PMID 33663470, 2021). "Primitive neuroectodermal tumors (PNET) coexpress CD57, CD99, and CD56." (PMID 39767137, 2024). "It is hypothesized that miR-125b induces chemoresistance in ES/primitive neuroectodermal tumors 59, and that miR-30a-5p interacts with the 3'UTR region of CD99 to regulate its expression." (PMID 31949491, 2020). "CD99 was negative, so primitive neuroectodermal tumor (PNET) was interpreted as negative." (PMID 25506006, 2014). "The negative CD99 study made a primitive neuroectodermal tumor (PNET) unlikely." (PMID 25254132, 2014).
leukemia (16 papers, 2014 to 2026). A malignant (clonal) hematologic disorder, involving hematopoietic stem cells and characterized by the presence of primitive or atypical myeloid or lymphoid cells in the bone marrow and the blood. "Another study identified a leukemia-associated immunophenotype (LAIP) of CD25+/CD34+/CD99+/CD123+ that is strictly associated with FLT3 ITD in AML with NPM1 mutation and a normal karyotype." (PMID 39594810, 2024). "CD99, a 32-kD transmembrane protein, is a leukemia associated phenotype marker used for the positive diagnosis of T-ALL." (PMID 27764235, 2016). "This research identifies a mechanism that regulates critical intercellular interactions within the CNS leukemia niche and supports the targeting of CD99 as a potential approach for overcoming meningeal-mediated leukemia chemoresistance." (PMID 40427525, 2025). "Significant CD99 expression has been noted in EWS and various forms of leukemia, including ALL, AML, and stem cells associated with MDS." (PMID 40427525, 2025). "In the CD34+CD38–TIM3+CD99+ leukemia stem cell–enriched (LSC-enriched) fraction, RUNX1mut LSCs (SU371) exhibited higher expression of IL-3RA compared with matched RUNX1wt LSCs (SU524, SU770)." (PMID 37581927, 2023). "CD99 is a potential targeting antigen for CAR T immunotherapy of CD99+ leukemia cells, preventing the development of several hematologic malignancies." (PMID 37112766, 2023). "This work provides insights into the role CD99 plays in the CNS leukemia niche and supports directly targeting CD99, or modulating its downstream pathways, as potential approaches for overcoming meningeal-mediated leukemia chemoresistance." (PMID 34934147, 2021). "We showed that CD99 is expressed on meningeal cells and that CD99 ligation with a monoclonal antibody disrupts adhesion between leukemia and meningeal cells and restores sensitivity of the leukemia cells to chemotherapy." (PMID 34934147, 2021). "Here, we isolated a low-affinity CD99 (12E7) antibody, which specifically recognizes leukemia cells over normal blood cells." (PMID 34627328, 2021). "Herein, we show that an antibody targeting CD99, a transmembrane protein expressed on meningeal cells and many leukemia cells, disrupts adhesion between leukemia and meningeal cells and restores sensitivity of the leukemia cells to chemotherapy." (PMID 34934147, 2021). "Apart from its role in EWS, CD99 was found to be frequently overexpressed in several types of leukemia, including acute lymphoblastic leukemia (ALL), acute myeloid leukemia (AML) and stem cells in myelodysplastic syndromes (MDS)." (PMID 29305692, 2018). "Time to leukemia onset was reduced compared to the primary animals (2–9 weeks) and in pt 4, the engraftment delay between CD99+ and CD99- subpopulations was reduced to 12 days." (PMID 27764235, 2016). "In addition to the direct effects of induced cytotoxicity on T-ALL cells, antibodies targeting CD99 have been shown to disrupt the adhesion between leukemia cells and meningeal cells by inducing matrix metalloprotease activity." (PMID 40427525, 2025). "Regarding acute myeloid leukemia (AML) and myelodysplastic syndromes (MDS), higher expression of CD99 has been linked to leukemia-initiating cells compared to normal hematopoietic cells." (PMID 40427525, 2025). "Previously, our group identified the 12E7 scFv, a low-affinity CD99 antibody that specifically recognizes leukemia cells over normal blood cells, which could prevent CAR T fratricide." (PMID 37112766, 2023). "As expected, genes associated with AML proliferation (FLT3, KIT), leukemia stem cells (CD34, CD38, and IL1RAP), and candidate genes overexpressed in AML (CD99, CD200, and LAMP2) were downregulated after chemotherapy, consistent with recent scRNA-Seq and immunohistochemistry data." (PMID 36099049, 2022). "Herein, we explored the role of CD99 in leukemia-meningeal interactions." (PMID 34934147, 2021).
leukemia (continued). "Moreover, CD99 is often expressed on myeloid and lymphoid leukemia cells and can both aid in leukemia diagnosis and correlate with prognosis." (PMID 34934147, 2021). "However, CD99 expression occurs in many normal tissues and a wide variety of tumor types, including other SRCSs, and lymphoblastic lymphoma, and leukemia." (PMID 33919988, 2021). "In general, data obtained in both EWS and leukemia indicate that CD99-induced cell death occurs preferentially in cells with an aberrant genetic background, thus conferring selectivity of anti-CD99 approaches against tumor cells." (PMID 29305692, 2018). "When ALL cells were sorted and assessed in functional assays, all 4 subpopulations (CD34+/CD99+, CD34+/CD99-, CD34-/CD99+ and CD34-/CD99-) could proliferate in vitro and establish leukemia in NSG mice." (PMID 27764235, 2016). "Lymphoblastic lymphoma and the leukemia group of tumors are also an important diagnostic consideration, as they can be positive for CD99 and negative for epithelial markers." (PMID 25475214, 2014). "Interestingly, studies have demonstrated direct interactions between CD99 expressed in leukemia cells and meningeal cells in the central nervous system (CNS), enhancing leukemia chemotherapy resistance by affecting the balance of leukemia apoptosis and the cell cycle." (PMID 40427525, 2025). "This evidence suggests that CD99-induced cell death primarily occurs in tumors with abnormal genetic backgrounds, such as EWS and leukemia, thereby providing selectivity." (PMID 40427525, 2025). "Targeting FLT3 or CD99 induces apoptosis in FLT3-ITD+ AML in vitro and reduces leukemia burden in vivo." (PMID 39007347, 2024). "CD34, CD99, and CD43 are also sensitive markers for the diagnosis of lymphoblastic lymphoma/leukemia." (PMID 35372059, 2022). "On sorting, the CD34+/CD99+ and CD34-/CD99+ subpopulations represented the majority of leukemia blasts (31.5±43% and 62.2±44%, respectively), while the CD34+/CD99- subpopulation was the smallest (0.40±0.7%)." (PMID 27764235, 2016). "Another mechanism through which CD99 contributes to the aggressiveness of AML may include its ability to enhance transendothelial migration and mobilization of malignant leukemia cells." (PMID 40427525, 2025). "Together, our results demonstrate that anti-CD99 CAR T cells could specifically recognize and efficiently eliminate CD99+ leukemia cells." (PMID 34627328, 2021). "Despite high levels of CD99 antigen on the majority of blast cells, leukemia initiating capacity in vivo was not restricted to cells that express this protein." (PMID 27764235, 2016).
solitary fibrous tumor (15 papers, 2010 to 2025). Solitary fibrous tumor (SFT) represents a diverse group of ubiquitous rare spindle cell neoplasms that may be benign or malignant and that most frequently arises from the pleura and peritoneum and rarely from other sites such as head and neck, liver and skeletal muscle. "In the present case, focal positivity for STAT6, Bcl-2, and CD99 supported the diagnosis of dedifferentiated solitary fibrous tumor (DSFT)." (PMID 40728762, 2025). "Immunohistochemical analysis demonstrated positivity for CD34, STAT6, MyoD1, α-SMA, Bcl-2, and CD99, confirming the diagnosis of extrapleural dedifferentiated solitary fibrous tumor (DSFT)." (PMID 40728762, 2025). "Positive expression for CD99 and Bcl2 is present in both sinonasal sarcoma and solitary fibrous tumors." (PMID 41226013, 2025). "Positive staining of the tumor markers, CD34+, CD99+ and Bcl-2+, was confirmed by pathological examination following surgery, and a solitary fibrous tumor of the spermatic cord was diagnosed." (PMID 25452776, 2015). "Given that the specimen revealed cells strongly positive to CD34 antibody and focal CD99 membranous expression, the diagnosis was in favour of a solitary fibrous tumor." (PMID 22035205, 2011). "Bcl-2 and CD99 immunohistochemistry were used to distinguish a hemangiopericytoma from a solitary fibrous tumor because a solitary fibrous tumor is positive for Bcl-2 and CD99." (PMID 20205807, 2010). "This characteristic helps distinguish desmoid tumors from other tumors that show fibroblastic proliferation, such as solitary fibrous tumors or nodular fasciitis, which more commonly demonstrate positivity for CD34, vimentin, Bcl-2 and CD99." (PMID 41226994, 2025). "Among these conditions is the intrapulmonary solitary fibrous tumor, which is usually positive for CD34, BCL2, CD99, and, more recently, STAT6." (PMID 40026987, 2025). "Other studies show that solitary fibrous tumors express CD34 in 80–95% cases and CD99 in 70%, while infrequently expressing Bcl2, epithelial membrane antigen, and smooth muscle actin (20–35% of cases)." (PMID 41226013, 2025). "Positiveness for antigens CD-99 and bCl-2 is similar to that of solitary fibrous tumor; nonetheless, CD-34 varies its reaction and is not inconstantly positive for hemangiopericytoma." (PMID 22499385, 2012). "However spindle cells in solitary fibrous tumor also express CD99 and bcl-2, which are negative for dermatofibrosarcoma protuberans." (PMID 23199263, 2012). "Immunohistochemistry confirmed the diagnosis of a solitary fibrous tumor with positive B-cell lymphoma 2, STAT6, and CD99, negative S100 and smooth muscle actin, and low levels of Ki67 (5–7%)." (PMID 37742027, 2023). "Immunohistochemistry (IHC) confirmed the diagnosis of a solitary fibrous tumor with positive B-cell lymphoma 2 (BCL2), STAT6, CD34, and CD99 and negative S100 and smooth muscle actin (SMA)." (PMID 37742027, 2023). "But these expressions were not decisive in the differentiation between solitary fibrous tumor and pancreatic hamartoma, because CD34 was positive for both tumors, and CD99 and bcl-2 expressions were not elucidated in the previous cases of pancreatic hamartomas." (PMID 26425382, 2015).